MS4A1 (membrane spanning 4-domains A1)
Diseases named in the same sentence as MS4A1 in open-access papers (continued):
Sharing a sentence is not in itself a finding about the gene and the disease.
cancer (continued). "Of the non-T-cell related targets, the proteins currently most widely targeted are ERBB2 (HER2), EGFR, MS4A1 (CD20), CD22, PDCD1 (PD-1), MSLN (mesothelin), and ERBB3 (Her3), all for cancer indications." (PMID 28822103, 2018). "In the gene co‐expression network, we observed that YRDC was associated with the expression of multiple immune cell signature genes at the pan‐cancer level, including T‐cell signature genes (CD3D, CD4, CD8A, CD8B), B‐cell signature genes (CD19, MS4A1), and multiple immunoglobulin genes." (PMID 40898423, 2025). "For instance, HMGB1, HMGB2, and MS4A1 were hypomethylated and highly expressed, whereas hypermethylation of genes such as LDB1, NDUFS2, and POU2F2 led to their reduced expression, reinforcing the impact of DNA methylation on gene dysregulation in cancer." (PMID 40396172, 2025). "Additionally, in vitro experiments were conducted to examine the effects of MS4A1 and TNFRSF17 on cancer proliferation, migration, invasion and other phenotypes." (PMID 36203424, 2022). "Importantly, both MS4A1 and TIL-B levels are consistently prognostic across five cancer types, namely HNSCC, LUAD, CESC, LGG, and KIRP, with distinct Be2 and BK signatures (especially for IL2, IL6, and PD-L2 expressions)." (PMID 32398659, 2020). "Instead, MS4A1, TIL-B, or potentially GPR18 may represent more versatile B-cell markers for prognosis in human cancers." (PMID 32398659, 2020). "Though methylation could silence the expression of MS4A1 gene, MS4A1 gene methylation only negatively correlated with CD20 protein expressions in two cancer types." (PMID 32398659, 2020). "Additionally, volcano plots of the differentially expressed genes in these cancers indicated that in the RAC1 low-expression group, the expression levels of B cell surface markers (such as CD19, CD79A, and MS4A1) and immunoglobulin-related genes (such as IGHG1 and CR2) were higher." (PMID 39898257, 2025).
infection (2 papers, 2024). The state of being infected such as from the introduction of a foreign agent such as serum, vaccine, antigenic substance or organism. "The upregulation of genes encoding B cell surface molecules—including CD19, MS4A1, CD22, FCER2, and CR1—may be involved in the proliferation and differentiation of memory B cells induced by the vaccine doses, following BA.5 infection." (PMID 39499071, 2024). "Elevated MS4A1, which encodes for CD20, in SAT resulting from infection without vaccination highlights the presence of an immune response." (PMID 38474155, 2024).
colon polyps (1 paper, 2022). "The results showed that patients with CC with high MS4A1 expression had early T- and pathological-stage CC and a more frequent history of colon polyps." (PMID 36203424, 2022).
inflammatory myopathy (1 paper, 2025). "Additionally, B-cell markers (MS4A1) and plasma cell markers (JCHAIN and SDC1) were significantly elevated compared to most other inflammatory myopathy groups, reaching levels akin to those seen in IBM muscle biopsies." (PMID 40568658, 2025).
MS4A1 also shares sentences with these, for which no sentence is quoted: mantle cell lymphoma (4 papers); glioma (2); heart failure (2); MALT lymphoma (2); marginal zone lymphoma (2); neutropenia (2); Obesity (2); primary immunodeficiency (2); rheumatoid arthritis (2); Anxiety (1); asthma (1); autoimmune thyroid disease (1); bladder carcinoma (1); breast invasive carcinoma (1); carcinoma in situ (1); cardiac hypertrophy (1); cervical squamous cell carcinoma (1); chronic leukemia (1); diabetes (1); endocervical adenocarcinoma (1); gastric tumors (1); glioblastoma (1); head and neck squamous cell carcinoma (1); hepatocellular carcinoma (1); idiopathic membranous nephropathy (1); Immunodeficiency (1); inflammatory bowel disease (1); influenza (1); kidney failure (1); leukemia (1).
A further 18 diseases each share a sentence with MS4A1 in 1 paper.